IFNA7 (interferon alpha 7)
Description:
Produced by macrophages, IFN-alpha have antiviral activities. Interferon stimulates the production of two enzymes: a protein kinase and an oligoadenylate synthetase.
Synonyms: IFNA-J; IFN-alphaJ
Tractability: Antibody: a drug acting on it is in phase 2 or 3 trials; its Gene Ontology location is reachable by antibodies, with high confidence; UniProt places it where antibodies can reach, with medium confidence; UniProt predicts a signal peptide or a membrane-spanning region.
Gene: Protein-coding gene on chromosome 9 (21,201,469 to 21,202,205, reverse strand). Ensembl gene ENSG00000214042.
Subcellular location: Secreted
Pathways (Reactome):
Immune System: Interferon alpha/beta signaling; Regulation of IFNA/IFNB signaling; TRAF6 mediated IRF7 activation
Disease: Evasion by RSV of host interferon responses; SARS-CoV-2 activates/modulates innate and adaptive immune responses
Hemostasis: Factors involved in megakaryocyte development and platelet production
Gene Ontology:
Molecular function: cytokine activity; type I interferon receptor binding; cytokine receptor binding
Biological process: adaptive immune response; B cell activation involved in immune response; cell-cell signaling; cellular response to virus; humoral immune response; natural killer cell activation involved in immune response; response to exogenous dsRNA; response to virus; T cell activation involved in immune response; type I interferon-mediated signaling pathway; defense response
Cellular component: extracellular region
Genetic constraint (gnomAD): Loss-of-function variants: 0 observed, 0.0767 expected, observed/expected ratio (o/e) 0, 90% interval 0 to 1.89. That is too few expected variants to judge how well the gene tolerates losing a copy. Missense variants: 278 observed, 215.36 expected, observed/expected ratio (o/e) 1.29, 90% interval 1.17 to 1.43. Synonymous variants: 119 observed, 80.99 expected, observed/expected ratio (o/e) 1.47, 90% interval 1.26 to 1.71.
Homologues: Orthologues: macaque IFNA10 (88% identical), macaque IFNA21 (87% identical), pig IFN-ALPHA-9 (67% identical), pig IFN-ALPHA-13 (66% identical), pig IFN-ALPHA-15 (66% identical), pig IFN-ALPHA-8 (66% identical), pig IFNA1 (65% identical), pig IFN-ALPHA-4 (63% identical), mouse Ifna15 (63% identical), pig IFN-ALPHA-17 (63% identical), pig IFN-ALPHA-1 (62% identical), pig IFN-ALPHA-10 (62% identical), and 32 more. Paralogues in human: IFNA4 (94% identical), IFNA10 (92% identical), IFNA17 (92% identical), IFNA21 (88% identical), IFNA16 (86% identical), IFNA14 (81% identical), IFNA5 (80% identical), IFNA2 (78% identical), IFNA6 (78% identical), IFNA8 (78% identical), IFNA1 (77% identical), IFNA13 (76% identical), and 4 more.
Diseases named in the same sentence as IFNA7 in open-access papers:
IFNA7 is named in the same sentence as 15 diseases in open-access papers, as found by Europe PMC text mining. Sharing a sentence is not in itself a finding about the gene and the disease. The quoted sentences say what the papers report.
COVID-19 (2 papers, 2023). A disease caused by infection with severe acute respiratory syndrome coronavirus 2. "Cytokine IFNA7, as well as chemokines CXCL13, CXCL10, CCL7, and CCL8 were present in the proteins selected for predicting severe COVID-19." (PMID 37069249, 2023). "This exercise revealed that, whereas the DS IFN score tracks preferentially with IFNG and IFNL1 in DS, this same ISG signature correlates significantly with eight different IFNs in COVID-19, five of which are type I IFNs (i.e., IFNA2, IFNA7/17/21, IFNA1, IFNA4/16, and IFNA10)." (PMID 37379383, 2023).
influenza (1 paper, 2023). An acute viral infection of the respiratory tract, occurring in isolated cases, in epidemics, or in pandemics; it is caused by serologically different strains of viruses (influenzaviruses) designated A, B, and C, has a 3-day incubation period, and usually lasts for 3 to 10 days. "Similar to influenza stimulation, vaccinia-stimulated PBMCs and monocytes shared multiple interferon-encoding genes, such as IFNA7, IFNA17, among their top DEGs." (PMID 37600811, 2023).
lung adenocarcinoma (1 paper, 2022). A carcinoma that arises from the lung and is characterized by the presence of malignant glandular epithelial cells. "We found CD1A|CXCL13, CD1A|S100A7L2, IFNA7|CMTM2, IFNA7|CSF3, CAMP|TFR2, this 5‐IRGPs were strongly associated with the prognosis of patients, all of which were protective factors for the prognosis of lung adenocarcinoma." (PMID 35246970, 2022).
lymphoma (1 paper, 2018). A malignant (clonal) proliferation of B- lymphocytes or T- lymphocytes which involves the lymph nodes, bone marrow and/or extranodal sites. "In addition, we observed co-expression of immune mediators, such as interferons and their targets (IFNA1-2, IFNA7-8, IFNB1, and IFNG), as well as proinflammatory cytokines (IL-1B and IL12B) and chemokines and their receptors (CXCL9-11 and CXCR3) by CpG(B)-STAT3dODN-treated lymphoma cells (right)." (PMID 29433938, 2018).
infection (5 papers, 2017 to 2023). The state of being infected such as from the introduction of a foreign agent such as serum, vaccine, antigenic substance or organism. "The RNA levels of many type I IFN genes, including Ifna13, Ifna7, Ifna1/5/6, Ifna1/2/5, Ifna4, Ifnab, Ifna12, and Ifnb1, were significantly increased in IEC4.1 cells 24 h post-infection." (PMID 36928642, 2023).
tumor (2 papers, 2012 to 2025). "The relative overexpression of IL13RA2 and underexpression of CXCL11 and IFNA7 also imply tumor-related chronic inflammatory suppressive TME which would support immune evasion." (PMID 41511314, 2025).
IFNA7 also shares sentences with these, for which no sentence is quoted: bacterial infections (1 paper); cancer (1); fungal infections (1); glioma (1); lung carcinoma (1); lupus nephritis (1); ovarian carcinoma (1); serous ovarian cancer (1); ZIKV infection (1).